PLXDC2 (plexin domain containing 2)
Diseases named in the same sentence as PLXDC2 in open-access papers (continued):
Sharing a sentence is not in itself a finding about the gene and the disease.
tumor (continued). "Plxdc2 (Plexin domain containing 2) is less well characterized than Camk1d, but it has been described as highly expressed endothelial tumor marker involved in angiogenesis, and a transmembrane receptor for Pigment Epithelium Derived Factor." (PMID 28792545, 2017). "The analyses showed that upregulation of PLXDC2 was positively correlated with Neoplasm Histological Grade (P = 0.000), TNM Stage (P = 0.000), T Stage (P = 0.007), N Stage (P = 0.008), but not with Age (P = 0.205), Sex (P = 0.147), Tumor Size (P = 0.916) and Tumor Location (P = 0.369)." (PMID 35661947, 2022). "Moreover, the intensity of PLXDC2 staining in tumor tissues was increased with invasion depth (Fig. 1aII–IV)." (PMID 35661947, 2022). "To further study the potential clinical relevance of PLXDC2 expression in tumor progression, we made use of 67 TMA with adequate PLXDC2 and CD163 staining effect of GC patient samples to compare the expression of PLXDC2 between GC tumor tissues and stromal tissues." (PMID 34124056, 2021). "Importantly, among them, we focused on Plexin domain containing 2 (PLXDC2) which is a component of the tumor endothelial marker (TEM) family." (PMID 34777633, 2021). "Similarly, Plxdc1 was first described in a screen for novel tumor endothelial members and expression of both Plxdc1 and Plxdc2 is elevated in the endothelium of solid tumors." (PMID 33657166, 2021). "Furthermore, according to a tissue microarray immunohistochemistry analysis, the expression of PLXDC2 elevated in human GC stromal specimens compared to tumor tissue specimens." (PMID 34124056, 2021). "The function of our key gene in EMT may indicate that PLXDC2 is a regulator of tumor metastasis." (PMID 34124056, 2021). "Peptide‐mediated inhibition of the PLXDC2‐cortactin binding led to a reduction in the mRNA levels of the tumor‐related genes MYC (p < 0.05) and POU5C1, and the proliferation‐related gene MKI67 (p < 0.05), while the mRNA levels of PLXDC2 and cortactin remained unchanged." (PMID 41365610, 2025). "Most importantly, comparison of PLXDC2 protein expression between paired pre- and post-IR tumor tissues from patients with HNSCC who did not respond to radiotherapy further demonstrated that PLXDC2 expression can be induced during treatment." (PMID 37089864, 2023). "Consistently, the co-localization of PLXDC2 and PTP1B was also observed in fresh GC tumor tissues." (PMID 35661947, 2022). "No such functional requirement for Plxdc2 in this process has been demonstrated, although it is upregulated in stromal endothelial cells of various tumours, including human colorectal cancer and glioblastoma." (PMID 21283688, 2011). "The data above might lead us to the conclusion that PLXDC2 affects tumor metastasis in a non-lymphatic manner." (PMID 34124056, 2021). "Comparison of PLXDC2 expression level in different samples (metaplasia, normal, PBMC, and tumor) was established, and the result showed that PLXDC2 scarcely express in the normal sample, while upregulating in PBMC and tumor samples in both macrophages and fibroblasts, and metaplasia in macrophages." (PMID 34124056, 2021). "In contrast to a recent study, despite being the closest homolog of PLXDC2, PLXDC1 was not significantly differentially expressed between tumor samples and normal samples at the gene level, leaving PLXDC2 as the only TEM suitable for predicting the survival outcomes of GC." (PMID 34124056, 2021). "However, there is no distinct difference between PLXDC2 expression and tumor specimens just based on the TGCA datasets." (PMID 34777633, 2021). "Along with single-cell study’s result that PLXDC2 is an important stromal related cell and the GSEA result that PLXDC2 affects EMT, our results point to the fact that PLXDC2 supports tumor invasion via a non-lymphatic, EMT related method." (PMID 34124056, 2021).
cancer (10 papers, 2011 to 2025). A tumor composed of atypical neoplastic, often pleomorphic cells that invade other tissues. "Moreover, loss of PLXDC2 suppressed the self-renewal capacity of cancer cells as evidenced by a reduced number of tumorspheres in either radioresistant or parental CAL27 cells." (PMID 37089864, 2023). "Thus, we inferred that PREX2, ADAMTS12, and PLXDC2 mutations lead to cancer development at both the protein function and posttranscriptional regulation levels." (PMID 35654793, 2022). "Notably, some identified 3′-UTR piSNV-affected genes, such as PREX2, ADAMTS12, and PLXDC2, were regarded as cancer-related genes with a high deleterious mutation rate." (PMID 35654793, 2022). "Immunohistochemistry method verified our in silico result that PLXDC2 is a vital metastatic related gene that effect within the stroma of cancer patients." (PMID 34124056, 2021). "These experiments uncover a direct molecular activity of Plxdc2 in the control of proliferation, of relevance in understanding the role of this protein in various cancers, where its expression has been shown to be altered." (PMID 21283688, 2011). "Expression of Plxdc2 is also altered in other cancers and in a number of conditions where a balance between proliferation, apoptosis and cellular arrest is involved." (PMID 21283688, 2011). "Recently, aberrant expression of PLXDC2 in cancers has been reported." (PMID 35661947, 2022). "The results above approved PLXDC2’s important role of promoting cancer metastasis in the stroma." (PMID 34124056, 2021). "Interestingly, another PEDF receptor, PLXDC2 was found to be expressed in a variety of cancers, including colon cancer, hepatocellular carcinoma, laryngeal cancer, testicular seminoma, and vulva squamous cell carcinoma." (PMID 35201465, 2021). "PLXDC2 is a transmembrane receptor for the multifunctional pigment epithelium-derived factor important for neural growth, stem cell development, angiogenesis, and cancer cell growth, among other functions." (PMID 30456346, 2018). "There is convergent evidence from several sources that the expression of Plxdc2 may be dynamically regulated in response to cellular stresses or in unusual cellular contexts, including cancer." (PMID 21283688, 2011). "PLXDC2-mediated signaling could be responsible for the direct effect of PEDF on cancer cells." (PMID 35201465, 2021).
infection (2 papers, 2020 to 2021). The state of being infected such as from the introduction of a foreign agent such as serum, vaccine, antigenic substance or organism. "Additional in vivo loss of function studies confirmed Plxdc2 regulatory function and its ability to shape the host immune response during infection with H. pylori and in a mouse model of IBD." (PMID 32661418, 2020). "Similar to the in vitro results, Plxdc2 deficiency significantly reduced bacterial colonization at day 28 post infection." (PMID 32661418, 2020). "Overall, we observed a weak reduction of infection by RRV gH-AELAAN by siRNA mediated knockdown of Plxdc2 expression, and comparatively potent and specific inhibition by one out of two rabbit antisera to Plxdc2." (PMID 33657166, 2021). "Preincubation of RRV with soluble Plxdc2 decoy receptor reduced infection by ~60%, while overexpression of Plxdc1 and 2 dramatically enhanced RRV susceptibility and cell-cell fusion of otherwise marginally permissive Raji cells." (PMID 33657166, 2021). "At day 28 post-infection Plxdc2−/− mice had a significant increase in inflammatory cells infiltrating the gastric mucosa and submucosa, which was accompanied by more severe mucosal hyperplasia in comparison to the WT group." (PMID 32661418, 2020). "The changes observed in the dynamics of Plxdc2 over the time course and the gastric microenvironment switch during the in vivo infection, suggest additional signaling mechanisms with impact on anti-bacterial and overall immune responses." (PMID 32661418, 2020). "RRV 26–95 infection was enhanced by both Plxcd1 and Plxdc2 expression and similarly RRV 26–95 gH/gL or gH alone facilitated fusion with Plxdc1 or Plxdc2 overexpressing Raji cells." (PMID 33657166, 2021). "In agreement with reduced infection of Eph- and Plxdc-binding virus mutants on HaCaT cells, EPHB3 and PLXDC2 expression was detected in HaCaT cells in published datasets (GSE95080, GSE138800) and by confirmatory qPCR of our samples." (PMID 33657166, 2021). "Even though the effect of Plxdc1/2 overexpression on RRV-YFP ΔgL infection was slightly less pronounced than the effect on RRV-YFP wt and RRV-YFP gH-AELAAN infection, this data demonstrates that the use of Plxdc1 and Plxdc2 as RRV 26–95 entry receptors is possible in a gL-independent manner." (PMID 33657166, 2021). "Similarly, knock-down of Plxdc2 alone did not lead to a decrease in RRV-YFP wt infection, which is probably explained by the expression of a multitude of Eph family receptors on 293T and relatively weak knockdown." (PMID 33657166, 2021). "At a minimum, our data on RRV-YFP ΔgL infection of Plxdc1 and Plxdc2 overexpressing Raji cells confirms that RRV can efficiently use Plxdc1 and Plxdc2 as entry receptors in the absence of gL." (PMID 33657166, 2021).
PLXDC2 also shares sentences with these, for which no sentence is quoted: meningioma (3 papers); COVID-19 (2); inflammatory bowel disease (2); allergic rhinitis (1); Angina (1); basal cell carcinoma (1); dilated cardiomyopathy (1); head and neck cancer (1); Hypertension (1); hypertrophic cardiomyopathy (1); Lymphatic Metastasis (1); male infertility (1); normal-tension glaucoma (1); Obesity (1); pulmonary fibrosis (1).